LGI1 (leucine rich glioma inactivated 1)
Diseases named in the same sentence as LGI1 in open-access papers (continued):
Sharing a sentence is not in itself a finding about the gene and the disease.
autosomal dominant lateral temporal lobe epilepsy (25 papers, 2011 to 2025). "In humans, mutations in LGI1 have been implicated in autosomal dominant lateral temporal lobe epilepsy." (PMID 41143948, 2025). "This study aimed to explore the pathomechanism of a mutation on the leucine‐rich glioma inactivated 1 gene (LGI1) identified in a family having autosomal dominant lateral temporal lobe epilepsy (ADLTE), using a precise knock‐in mouse model." (PMID 34767694, 2022). "In humans, at least 43 mutations in the LGI1 gene are known to be associated with autosomal dominant lateral temporal lobe epilepsy (ADLTE)." (PMID 36428502, 2022). "Autoantibodies against LGI1 are linked to seizures and cognitive dysfunction, and it is well established that variants in LGI1 are causative for autosomal dominant lateral temporal lobe epilepsy." (PMID 35457207, 2022). "PBA also lessened trafficking defects for an ER-retained LGI1 mutant associated with autosomal dominant lateral temporal lobe epilepsy, LGI1(E383A)." (PMID 35327449, 2022). "Mutations in LGI1, which encodes a neuronally-secreted protein, cause autosomal dominant lateral temporal lobe epilepsy (ADLTE)." (PMID 35250833, 2022). "The mutations of LGI1 cause autosomal dominant partial epilepsy with auditory seizures (autosomal dominant lateral temporal lobe epilepsy: ADLTE)." (PMID 32668637, 2020). "Mutations in leucine-rich glioma-inactivated protein 1 (LGI1) causes autosomal dominant lateral temporal lobe epilepsy in humans." (PMID 30225353, 2018). "Mutations in LGI1 in humans causes autosomal dominant lateral temporal lobe epilepsy and homozygous deletion of LGI1 in mice results in severe epileptic seizures that cause early postnatal death." (PMID 30225353, 2018). "LGI1 cysteine mutations have been associated with autosomal dominant lateral temporal lobe epilepsy." (PMID 26275289, 2015). "Mutations in LGI1 are responsible for autosomal dominant lateral temporal lobe epilepsy (ADLTE), an inherited syndrome characterized by seizure and hallucinations." (PMID 25591666, 2015). "LGI1 is highly expressed in the hippocampus and the neocortex, and mutations in the LGI1 gene cause autosomal dominant lateral temporal lobe epilepsy." (PMID 24950993, 2014). "Leucine-rich glioma inactivated 1 (Lgi1), a putative tumor suppressor, is tightly associated with autosomal dominant lateral temporal lobe epilepsy (ADLTE)." (PMID 30034322, 2018). "Here, we analyzed the Kir4.1 expressional changes in Leucine-Rich Glioma-Inactivated 1 (Lgi1) mutant rats, which is a model of autosomal dominant lateral temporal lobe epilepsy in humans, to clarify the role of astrocytic Kir4.1 channels in Lgi1-related epileptogenesis." (PMID 30813600, 2019). "Mutations in ADAM23 have not been found in epileptic patients, but it interacts with LGI1, a gene associated with familial temporal lobe epilepsy-1 (ETL1) in human and with LGI2, which is the causative gene for benign focal epilepsy in dogs." (PMID 22457775, 2012). "The interaction of LGI1 with ADAM22 and ADAM23 makes an important impact on the molecular mechanism of autosomal dominant lateral temporal lobe epilepsy (ADLTE)." (PMID 32655475, 2020).
thymoma (25 papers, 2018 to 2026). A neoplasm arising from the epithelial cells of the thymus. "We are presenting a very unusual case of LGI1 autoimmune LE with two additional autoantibodies, anti-acetylcholine receptor (AChR) and anti-striational, in a patient with an underlying thymoma." (PMID 37927656, 2023). "LGI1 antibodies only rarely associate with tumours, usually thymomas, which are more common in the patients with both LGI1 and CASPR2 antibodies." (PMID 31655889, 2021). "Although thymoma or thymic carcinoma has been reported to be associated with AE, the most common targets are LGI1, Caspr2 and γ-aminobutyric acid (GABA)- A type receptor antibody encephalitis." (PMID 31195997, 2019). "Based on observations over recent years, there were 3 autoantibodies of AE associated with thymoma involving anti‐AMPAR antibody, anti‐GABAA R antibody, and anti‐LGI1 antibody, which mainly targeted the limbic system in antibodies‐mediated AE." (PMID 38421083, 2024). "Tumor occurs in up to 46% of adult patients with LGI1-CASPR2 double-positive (generally thymoma) in the previous reports." (PMID 35463890, 2022). "Eleven of these patients (9%) were associated with tumors: 8 lung cancers (2 with LGI1 antibodies, 7 with GABAB antibodies), 1 colorectal adenoma (1 with LGI1 antibodies), 1 ovarian teratoma (1 with NMDAR antibodies), and 1 thymoma (1 with LGI1 antibodies)." (PMID 34899696, 2021). "Cancer is more frequent in CASPR2 compared to LGI1-antibody positive patients, more commonly with thymoma." (PMID 33396564, 2020). "The subgroup of patients with thymoma‐associated MG and NMT showed reactivities to known (CASPR2/LGI1) and to the recently identified (Netrin‐1 receptors) neuronal cell‐surface antibodies." (PMID 30714278, 2019). "In partial contrast, Netrin‐1 receptor antibodies (DCC plus UNC5A, or DCC alone) coexisted with both CASPR2 and LGI1 antibodies in two patients with Morvan syndrome and thymoma recurrence." (PMID 30714278, 2019). "Anti-LGI1 AE, among the most frequent types of AE overall, is also considered one the most frequent cause of non-paraneoplastic LE – although a non-negligible portion of anti-LGI1 AE cases is paraneoplastic, and specifically associated with thymomas." (PMID 38507081, 2024). "HLA-DRB1*11:01.Thymoma in ~20% (often with LGI1 antibodies in addition)Electromyography may demonstrate hyperexcitability (fasciculations, myokymia)." (PMID 34108243, 2021). "LGI1- and CASPR2-antibody encephalitis syndromes share significant overlap with regard to clinical and radiological phenotypes, yet patients with CASPR2 antibodies tend towards the neuromyotonia and Morvan’s phenotypes, and often have underlying thymomas." (PMID 31655889, 2021). "However, of the 6 patients with both CASPR2 and LGI1 antibodies, 3 (50%) had thymoma and 1 had developed prostate cancer; 1 had mild disease that responded to carbamazepine alone." (PMID 30242309, 2018). "First, AE patients frequently have some particular tumors, which might be associated with multiple anti-neuronal antibodies such as GABABR, Hu, SOX1, and CV2 antibodies in SCLC, or LGI1 and AMPAR antibodies in thymoma." (PMID 38163879, 2024). "Comorbid tumors (mainly thymoma and SCLC) occurred in <10% of patients with anti-LGI1 LE." (PMID 33396564, 2020). "Antibodies to the now well-recognized VGKC-complex antigens were present in 17 of the 38 patients (45%), but these included 6 (16%) patients with both LGI1 and CASPR2 antibodies, and these patients had more severe disease, thymoma (in 50%), and features of Morvan syndrome." (PMID 30242309, 2018). "For example, patients with LE and LGI1 antibodies rarely have a tumor, whereas at least 50% of patients with GABABR antibodies have SCLC,14,15 more than 50% of patients with AMPAR antibodies have thymoma, lung, or breast cancer, and most (>85%) patients with Hu antibodies have SCLC." (PMID 34006622, 2021).
thymoma (continued). "Moreover, although heterogeneity of clinical features and related antibodies may limit interpretation of significant correlations, the coexistence of LGI1 and CASPR2 antibodies may suggest the presence of thymoma, often accompanied by autonomic and central nervous system involvement." (PMID 30242309, 2018).
memory impairment (20 papers, 2014 to 2026). "These significant memory impairments have been associated with the integrity of neuroanatomical memory structures in patients with anti-LGI1 ab-mediated AE." (PMID 38918245, 2024). "Specifically, there is broad consensus that LGI1 ab-mediated AE patients can have significant primary memory impairments." (PMID 38918245, 2024). "Memory impairments, spatial disorientation, apathy, and sleep disorders were the commonly found residual symptoms in anti‐LGI1 patients, whereas memory impairments and seizures were common in anti‐GABABR patients." (PMID 32783406, 2020). "One patient tested positive for the LGI1 antibody in both blood and CSF, who got great improvement in seizure frequency and memory impairment after hormonotherapy." (PMID 25269594, 2014). "The prevalence of acute or subacute memory impairment was highest for CASPR2 (5/5) and LGI1 (73%) AE." (PMID 36831042, 2023).
Morvan syndrome (20 papers, 2013 to 2025). Morvan syndrome is a rare, life-threatening, acquired neurologic disease characterized by neuromyotonia, dysautonomia and encephalopathy with severe insomnia. "The most common phenotypic spectrum of LGI1-CASPR2 double-positive associated neurological disorders in children is Morvan syndrome, similar to adults." (PMID 35463890, 2022). "In the study, we describe two pediatric Morvan syndrome with LGI1-CASPR2 double-positive and present the results of the first systematic literature review on pediatric LGI1-CASPR2 double-positive cases." (PMID 35463890, 2022). "Herein, we present two children of Morvan syndrome with LGI1-CASPR2 double-positive and perform a systematic literature review of neurological disorders in children with double antibodies positivity." (PMID 35463890, 2022). "For Morvan's syndrome post-thymectomy with LGI1 antibody positivity, B-cell depletion therapy such as intravenous rituximab is an effective treatment." (PMID 36479084, 2022). "She had antibodies targeting CASPR2 and LGI1, tested by the indirect immunofluorescence test, which demonstrated the diagnosis of typical Morvan syndrome as well as classical limbic encephalitis." (PMID 26983964, 2016). "Through the detailed analysis of her clinical course, the diverse and overlapping clinical phenotype of CASPR2-Ab and LGI1-Ab in patients with Morvan syndrome was obvious and interesting." (PMID 26983964, 2016). "This case provides a rare female resource of Morvan syndrome, which is the first patient with both CASPR2-Ab and LGI1-Ab positive Morvan syndrome in China and one of the few female patients with Morvan syndrome reported so far." (PMID 26983964, 2016). "Our case also corresponded with the condition that Morvan syndrome is usually associated with high-titer CASPR2-Ab and often accompanied by lower-titer LGI1-Ab." (PMID 26983964, 2016). "Autoimmune CASPR2 and LGI1 diseases usually manifest as Morvan syndrome and/or limbic encephalitis." (PMID 37933002, 2023). "Our literature review on Morvan syndrome with LGI1-CASPR2 double-positive disclosed only two pediatric cases (2/12, 16.6%) with muscle cramps, which the lower number of pediatric patients might partially explain." (PMID 35463890, 2022). "Morvan syndrome (MoS) is a rare autoimmune syndrome associated with antibodies against two kinds of potassium channel proteins, contactin associated protein-like 2 (CASPR2) and leucine-rich glioma inactivated protein 1 (LGI1)." (PMID 33941099, 2021). "Plenty of studies have demonstrated the association between Morvan syndrome and antibodies to voltage-gated potassium channels (VGKC-Ab) including contactin associated protein-like 2 antibodies (CASPR2-Ab), leucine-rich glioma inactivated protein 1 antibodies (LGI1-Ab) and other antibodies." (PMID 26983964, 2016). "Here we report on a both CASPR2-Ab and LGI1-Ab positive female patient who presented with typical Morvan syndrome as well as classical LE, which is the first patient with double antibodies positive Morvan syndrome in China and one of the few female patients with Morvan syndrome reported so far." (PMID 26983964, 2016). "Besides, titer of CASPR2-Ab was always higher than that of LGI1-Ab, which indicated the association of CASPR2-Ab with PNH and Morvan syndrome." (PMID 26983964, 2016). "The patient was diagnosed with Morvan syndrome, based on the clinical presentation of CNS (dyssomnia, irritability, and fatigue), PNS (pain), and autonomic nervous system (excessive sweating, tachycardia, hypertension) associated with serum and CSF LGI1 and CASPR2 antibodies." (PMID 35463890, 2022). "Both anti-CASPR2 and anti-LGI1 antibodies are found in patients with Morvan syndrome, and the anti-CASPR2 antibody titer is higher than that of anti-LGI1 antibodies." (PMID 34421519, 2021).
Morvan syndrome (continued). "Amongst these, two patients showed polyreactivities that included the two Netrin‐1 receptor antibodies (CASPR2+LGI1+DCC+UNC5A and CASPR2+LGI1+DCC), both diagnosed as Morvan syndrome." (PMID 30714278, 2019). "From her treatment and clinical course, the diverse and overlapping effects of LGI1-Ab and CASPR2-Ab in Morvan syndrome were apparent." (PMID 26983964, 2016). "Through the detailed analysis of her clinical course, we aim to emphasis the diverse and overlapping clinical phenotype of LGI1-Ab and CASPR2-Ab in patients with Morvan syndrome." (PMID 26983964, 2016). "There are very few female Morvan syndrome cases with both CASPR2-Ab and LGI1-Ab positive." (PMID 26983964, 2016). "It was showed from the detailed analysis of clinical course that the combination of LGI1-Ab and CASPR2-Ab might contribute to distinct phenotype of Morvan syndrome." (PMID 26983964, 2016). "The diagnosis of Morvan syndrome was based on the combination of CNS (irritability, fatigue, episodes of crying, and dyssomnia), PNS (pain), and dysautonomia nervous system symptoms (tachycardia, skin rash, hypertension, and profuse sweating) as well as serum LGI1 and CASPR2 antibodies." (PMID 35463890, 2022).
autoimmune disease (18 papers, 2017 to 2025). A disorder resulting from loss of function or tissue destruction of an organ or multiple organs, arising from humoral or cellular immune responses of the individual to their own tissue constituents. "Limbic encephalitis (LE) associated with leucine-rich glioma-inactivated-1 (LGI1) antibodies is an autoimmune disease characterized by a subacute decline in memory, behavioral disturbances, and temporal lobe epilepsy." (PMID 40407616, 2025). "The patient tested positive for anti-LGI1 antibodies, and the authors hypothesized that inflammation caused by an autoimmune disease process may have contributed to MMS progression." (PMID 34539540, 2021). "Limbic encephalitis (LE) due to anti-leucine-rich glioma-inactivated 1 (LGI1) antibodies is an autoimmune disease characterized by distinct clinical features unique to LGI1 LE, such as faciobrachial dystonic seizures." (PMID 38473828, 2024). "The Leu-rich epitopes have also been shown to induce an IL-17 response in different autoimmune diseases such as NLRP3 (autoimmune encephalomyelitis), FLRT2 (systemic lupus erythematosus), and LGI1 (limbic encephalitis)." (PMID 29163505, 2017).
glioma (18 papers, 2008 to 2025). A benign or malignant brain and spinal cord tumor that arises from glial cells (astrocytes, oligodendrocytes, ependymal cells). "Specifically, VGKC includes leucine-rich glioma inactivated protein 1 (LGI1), which is implicated in glioma development." (PMID 40535121, 2025). "The loss of LGI1 expression in most high-grade gliomas supported the function of tumor suppressor gene." (PMID 20111625, 2009). "A role of LGI1 in the development of malignant brain tumors was substantiated by the discovery of somatic missense mutations in LGI1 gene associated with high- and low-grade gliomas." (PMID 20111625, 2009). "We found that Lgi1 is critical for the maintenance of myelin in the brain, suggesting that Lgi1 loss may contribute to glioma-related dysmyelination." (PMID 30034322, 2018). "LGI1 is also expected to be involved in suppression of cell migration, as increased expression of LGI1 in glioma cell lines reduced the proliferation and migration ability of these cells significantly." (PMID 36289737, 2022). "In consistent with previous report, our results showed Lgi1 expression was significantly attenuated in gliomas." (PMID 30034322, 2018). "The requirement for LGI4 for embryonic enteric glial cell and satellite cell proliferation contrasts with that of LGI1 for glioma cells as LGI1 inhibits proliferation of glioma cells." (PMID 23713523, 2013). "The first LGI gene to be identified, LGI1, was found at a chromosomal translocation breakpoint in a glioma cell line." (PMID 23713523, 2013). "In glioma cells, LGI1 re-expression reduces their ability to proliferate and form colonies on soft agar in one study, but not in another." (PMID 23713523, 2013). "Although LGI1 was identified initially from chromosomal breakpoint(s) in high-grade gliomas, and was proposed to function as a tumour suppressor gene, its role in oncogenesis remains controversial." (PMID 23713523, 2013). "The LGI1 gene was originally observed in glioma where increased expression of LGI 1 contributes to decreased proliferation of neuroblastoma cells." (PMID 23194409, 2012). "The gene LGI1 (leucine-rich gene – glioma inactivated) was discovered by positional cloning in 1998 and found to be mainly expressed in neural tissues, particularly in the brain." (PMID 18578868, 2008). "Meizan Lai’s research indicated that LGI1 may inhibit glioma metastasis, while Sarosh R. Irani focused on treatment and management strategies for autoimmune encephalopathy." (PMID 40535121, 2025). "Another intriguing question is that LGI1 may play roles in glioma genesis and oligodendrocyte differentiation and myelination." (PMID 36804022, 2023). "In contrast, co-expression of a neuronal marker and LGI1 in gliomas suggests that LGI1 expression levels in these tumours may relate to the number of trapped neurons, and ADPEAF patients do not show increased frequencies of glioma." (PMID 23713523, 2013). "The human leucine rich, glioma inactivated 1 (LGI1; GeneID 9211; MIM# 604619) gene has been linked to two different clinical phenotypes: malignant progression of glioma and autosomal dominant lateral temporal epilepsy (ADLTE; MIM# 600512), a rare familial partial epilepsy syndrome." (PMID 21479274, 2011). "Additionally, LGI1, which has tumor suppressor activity in glioma, showed an epileptogenic effect." (PMID 41007824, 2025). "Because the invasion and cell migration of glioma cells are suppressed by overexpression of LGI1, it is likely that the cytoarchitecture and developmental cell migration could be asymmetric between the left and right hemispheres due to the difference in the amount of LGI1 expression." (PMID 30253786, 2018). "Moreover, LGI1 overexpression inhibits the expression of MMPs, specifically MMP1 and MMP3, in glioma cells through the MAPK/ERK pathway." (PMID 36289737, 2022).
glioma (continued). "LGI1 expression is reduced or absent in many glioma cell lines; it also has been reported to be down-regulated in glioma tumours, in Barrett’s-related adenocarcinoma of the esophagus, and in prostate cancer." (PMID 23713523, 2013). "In agreement with this hypothesis the reexpression of LGI1 in glioma cells, lacking endogenous LGI1, impaired cell growth and migration capacity." (PMID 20111625, 2009). "Additionally, the effect of LGI1 expression on increasing AKT (protein kinase B) signalling, reducing ERK (extracellular-signal-regulated kinase) signalling, and reducing matrix metalloproteinase expression in glioma and other cells in culture may provide clues about its function in vivo." (PMID 23713523, 2013).